CASP1 (caspase 1)
Diseases named in the same sentence as CASP1 in open-access papers (continued):
Sharing a sentence is not in itself a finding about the gene and the disease.
infection (continued). "To further confirm the formation of this multiprotein complex, we observed the colocalization of ASC specks with AIM2 and CASP1 within the same cell at 24 h post-MPXV infection." (PMID 41225161, 2025). "We detected the expression of major inflammasome genes (NLRP3, caspase-1, IL-1β, IL-18) during infection progression." (PMID 40906404, 2025). "NLRP1, NLRP3, AIM2, and IFI16 inflammasome sensors regulate infection-induced caspase-1 activation and cleavage, allowing caspase-1-dependent pyroptosis." (PMID 40593504, 2025). "Next, we continued to investigate the role of caspase-1 and caspase-4 in the release of additional inflammatory mediators from gingival epithelial cells after infection with HK1651 for 24 h." (PMID 40137780, 2025). "They prevent excessive tissue damage during infection by exhibiting reduced function of important components like caspase-1 and IL-1β, as well as inhibited activation of the NLR family pyrin domain-containing 3 (NLRP3) inflammasome." (PMID 41009960, 2025). "Our findings indicated that MPXV infection promoted CASP1-dependent cleavage of CASP1 and the release of the inflammasome-driven cytokines IL-1β and IL-18, suggesting that MPXV is involved in inflammasome activation." (PMID 41225161, 2025). "The level was increased in the infection group compared with the control group (p < 0.01), while amoxicillin and probenecid treatment reduced cleaved caspase-1 expression compared with the infection group (p < 0.05)." (PMID 40305201, 2025). "Many components of the classical inflammasome that are activated by Salmonella42, including Nlrp3, Casp1 and Gsdmd, are among those transcriptionally upregulated after 120 min of infection with either strain of Salmonella." (PMID 41188240, 2025). "In IPEC-J2 cells, miR-215 overexpression during infection significantly reduced the IL1β and CASP1 gene expression (p < 0.01 and p < 0.05, respectively)." (PMID 39943201, 2025). "Macrophage cell cytotoxicity was investigated by quantifying the release of lactate dehydrogenase during infection and by determining cleavage of the proinflammatory markers caspase-1, gasdermin D, and prointerleukin-1β." (PMID 40037395, 2025). "Consistently, G. parasuis infection significantly up-regulated NLRP3, GSDMD, and caspase-1 expression at 24 h post-infection (hpi), indicating activation of the canonical pyroptotic pathway in PAMs." (PMID 40665414, 2025). "In the canonical pathway, intracellular pattern recognition receptors (such as NLRP3) detect infection or damage signals and assemble into inflammasomes, which subsequently activate pro-caspase-1, leading to the formation of active caspase-1." (PMID 39587093, 2024). "In KO THP-1dM cells, production of active caspase-1 was significantly reduced by Lt-P10 infection (p = 0.004), whereas IL-1β production was increased, although not significantly." (PMID 38707903, 2024). "After 5 weeks of infection, Casp1-/- mice exhibited a significantly higher lesion score, lesion size, and parasite burden than control C57BL/6 mice, and this difference continued to increase until 7 weeks p.i.." (PMID 39250503, 2024). "Further, the Western blot assays demonstrated that the P20 protein expression increased with the infection time after cleavage by caspase-1." (PMID 39728983, 2024). "While infection also reduced goblet cell numbers in the ceca of Casp1/11−/− mice, it was to a lesser extent than for infected WT mice." (PMID 39428744, 2024). "When macrophages were infected with a high dose of DENV-1 (MOI = 1), NLRP3 and GSDMD mRNA reached a peak value in the early stage of infection (h.p.i = 24 h), while the Caspase-1 mRNA level gradually increased with the infection time." (PMID 39767659, 2024). "Levels of the cleaved active form of caspase-1 and the caspase-1 activity were also higher in N2aC24L1-3 cells than in N2aC24 cells after IAV/WSN infection." (PMID 39194237, 2024).
infection (continued). "Together, these data suggest caspase-1 and Aβ can drive either salutary or deleterious effects in response to infection; however, the impact of pathogen virulence factors on the switch between these two properties remains poorly understood." (PMID 38410714, 2024). "But in the late stage of infection, ROS induced caspase-1-dependent microglia pyroptosis and IL-1β secretion." (PMID 37697221, 2024). "With IL-18 being a molecule released downstream of caspase-1, we were curious as to when during infection IL-18 is released." (PMID 39446964, 2024). "We infected Cx3cr1cre/+ x Caspase 1 fl/fl (Cx3cr1+Casp1 KO) and Cx3cr1+/+ x Caspase 1fl/fl (WT) littermate controls with 10 cysts Me49 and at eight days post infection we harvested tissues." (PMID 39446964, 2024). "The therapeutic potential of targeting caspase-1 has been largely explored; however, this strategy would also alter responses downstream of NLRP3 and result in increased susceptibility to infections." (PMID 39459869, 2024). "In the case of macrophage infection by V. vulnificus and V. cholerae, the NLRP3 inflammasome senses the infection, leading to caspase-1 activation and IL-1β secretion." (PMID 39186780, 2024). "Challenge of immunized mice with K. pneumoniae resulted in near identical lung burdens between the vaccinated wildtype and Casp1/4−/− mice 24 h post-infection." (PMID 38594380, 2024). "In vitro studies demonstrated that B19V abortive infection induces NLRP3-dependent caspase-1 activation and caspase-1 mediated IL-1β secretion in monocytic phorbol 12-myristate 13-acetate PMA-differentiated THP-1 cells." (PMID 39203550, 2024). "PI uptake was observed following infection, a process that was markedly reduced in presence of caspase-1 inhibitor, revealing inflammasome activation in L. mexicana-infected human neutrophils." (PMID 39250503, 2024). "We identified a caspase-1/IL-1RAP signaling axis as a necessary component of neutrophil recruitment to the site of infection." (PMID 39446964, 2024). "Casp1/11−/− mice also showed an infection-induced increase in IL-22, but at levels significantly lower than for WT infected mice." (PMID 39428744, 2024). "During productive infection, there is a notable surge in the number of cells exhibiting positive results for caspase 1, an enzyme activated subsequent to inflammasome formation." (PMID 38590522, 2024). "Probenecid and 25–100 mg/kg baicalin inhibited the mRNA levels of NF-kB, NLRP3 and Caspase-1 compared to those in the infection group (p < 0.05)." (PMID 39075542, 2024). "At day eight post-infection, we performed ELISAs on the serum and found that Cx3cr1+Casp1 KO mice had decreased IFN-γ levels, comparable IL-12 levels, and decreased IL-18 levels compared to WT mice." (PMID 39446964, 2024). "Our findings demonstrated that recognition of MDR A. baumannii 1605 infection by the host activates the caspase-1 and caspase-11, resulting in NLRP3/ASC inflammasome activation and the formation of GSDMD pores and induction of programmed cell death." (PMID 39533032, 2024). "Our previous studies using cell culture and animal models have described paradoxical functions of caspase-1 activation during infection." (PMID 38410714, 2024). "When we assessed caspase-1, we observed increased production of full length caspase-1 as well as a potentially active high molecular weight form of caspase-1 (which we refer to in our figures as aggregated caspase-1) at 24 hours post-infection." (PMID 37928185, 2023). "Nod-like protein 3 (NLRP3), along with ASC and caspase 1, is integral to the inflammasome, specifically in myeloid cells during infection." (PMID 37974615, 2023). "For instance, it was shown that both Casp1/11–/– and Casp8–/–Ripk3–/– mice resisted an intravenous Salmonella Typhimurium infection, while Casp8–/–Ripk3–/–Casp1/11–/– mice succumbed to this infection." (PMID 37080966, 2023).
infection (continued). "Quantitative analysis of protein levels performed by dot blot scanning showed that the expression levels of ACE-2, annexin-V, flotillin-1, TLR-7, LAMP, TNF-α, caspase-1, caspase-8, and others were altered in EVs after infection." (PMID 36979955, 2023). "Using immunoblotting-based biochemical analyses, we observed IAV-induced PANoptosis in BMDMs at both 12 and 24 h post-infection, as indicated by activation of CASP1, gasdermin D (GSDMD) and GSDME, along with CASP8, CASP3, and CASP7, as well as MLKL." (PMID 38005819, 2023). "We next infected both WT, CARD8 KO, or CASP1 KO THP-1 cells with WT HIV-1LAI or HIV-1LAI-VSVG viruses at an MOI that would give 30–50% infection of WT cells." (PMID 37417868, 2023). "Intriguingly, ablating Gsdmd on a Casp8–/–Ripk3–/– background did not reproduce the C. rodentium lethality phenotype as obtained after Casp1/11 deletion, as all Casp8–/–Ripk3–/–Gsdmd–/– mice survived the infection." (PMID 37080966, 2023). "In a previous study, our research group reported that the secretion of IL-1β was caspase 1-dependent during infection of bovine macrophages with the NADL cp-BVDV strain." (PMID 37515181, 2023). "Pyroptosis via NLRP3 and Caspase-1 was originally described as an antimicrobial response following infection by intracellular pathogens." (PMID 37487005, 2023). "Herein, we demonstrated that S. flexneri releases apyrase within the host cell cytoplasm during infection; due to its ATP-hydrolyzing activity, apyrase degrades iATP, thereby reducing the cell death rate of infected cells via preventing caspase-1 activation." (PMID 37795996, 2023). "In this study, Bacillus Calmette-Guerin (BCG) infection resulted in high expression of pro-caspase-1, caspase-1 p20, GSDMD-N, and p-PERK in the THP-1 macrophage, being downregulated with the pre-treatment of GSK2656157, a PERK inhibitor." (PMID 38003429, 2023). "Next, we compared the infections of WT, Nlrp3–/–, Gsdmd–/–, and Casp1/11–/– mice using metacyclic promastigotes." (PMID 36828815, 2023). "The combination of TMAO and CFT073 significantly increased caspase-1 activity compared to CFT073 infection alone." (PMID 37111409, 2023). "Although all animal groups showed similar levels of bacterial loads at 24 weeks post-infection, only Casp1−/− mice had increased inflammatory scores (p = 0.027) and stomach weights (p = 0.018) when compared with WT animals." (PMID 37365163, 2023). "Consistently, crotonate reduced NLRP3/caspase-1 dependent cleavage of the proinflammatory cytokine interleukin (IL)-1β at 3 and 6 h post-infection." (PMID 37929941, 2023). "Collectively, these data demonstrate that caspase-1 is required for the activation of pyroptosis in macrophages during infection." (PMID 37457695, 2023). "Platelets also suppressed the mRNA expression levels of pyroptosis-related genes (GSDMD and caspase-1) and displayed distinct modulation outcomes over the time of infection." (PMID 37486928, 2023). "The activation of caspase-1 is the key to the classical pyroptosis pathway, which is a defense mechanism against infection." (PMID 38089953, 2023). "The NLRP3 inflammasome is a critical component of the innate immune system mediating caspase-1 activation and proinflammatory cytokines secretion in response to harmful stimuli such as infection and endogenous stress." (PMID 36779699, 2023). "Casp1/11–/– and Gsdmd–/– mice infected with C. violaceum succumbed to infection between 3 and 9 dpi and had increased burdens in both the liver and spleen 3,5." (PMID 37865673, 2023). "We next assessed viability of WT, Nlrc4–/–, Casp1–/–, and Gsdmd–/– BMMs during FliCON infection using a lactate dehydrogenase (LDH) assay." (PMID 38055781, 2023). "Several Leishmania spp., including L. amazonensis, L. major, L. braziliensis and L. infantum chagasi, activate NLRP3- and ASC-dependent caspase-1 in macrophage cells, and the infection of Leishmania spp." (PMID 36869360, 2023).
infection (continued). "Among critical inflammation and immune response biomarkers, HSP100, TNF-α, TGIF-1, TGIF-2, mCCL22, iNOS, caspase-1, and caspase-8 were significant at different time points in the infection-derived EVs during CCoV infection of CRFK cells." (PMID 36979955, 2023). "In response to infection, there was a significant, Ch25h-dependent increase in Nlrp3, Pycard, and Casp1 gene expression observed at 24 h post-infection." (PMID 36831236, 2023). "Consistently, we found that cleaved product p10 of the caspase-1 activation generated during TX01∆fur2 infection was stronger than that of TX01 infection." (PMID 38276180, 2023). "Inhibition of caspase 1 via SC-236 resulted in lower expression of IL-1β on the mRNA and the secreted protein after infection with E. coli." (PMID 37697284, 2023). "For example, platelets significantly inhibited the expression of caspase-1 mRNA in macrophages at all DBV infectious doses at 72 h post-infection, while only reduced the expression of GSDMD when the DBV MOI was 0.1 or 0.0.1." (PMID 37486928, 2023). "RSV induces the activation of the NLRP3 inflammasome and caspase 1, and both events are crucial for the secretion of IL-1β, IL-33, and IL-18 during infection." (PMID 37508374, 2023). "The NLRP3 inflammasome is a critical component of the immune system that mediates caspase-1 (Casp1) activation and the secretion of the pro-inflammatory cytokines, interleukin (IL)-1β and IL-18, in response to infection and cell injury." (PMID 36894537, 2023). "Mature and functionally active 17 kDa IL-1β species can be generated by caspase-1 cleavage, and released at sites of infection/injury to regulate diverse physiological responses." (PMID 36519759, 2023). "ST infection markedly improved the mRNA relative expression levels of inflammasome biomarkers including Caspase-1, IL-1β and IL-18 compared with the control group (p < 0.05)." (PMID 37893938, 2023). "In contrast, Casp8+/-Ripk3–/–Casp1/11–/– mice disabled for necroptosis and pyroptosis cleared the infection with normal kinetics, in line with the ability of Gsdmd–/–Mlkl–/– mice to clear intestinal C. rodentium loads." (PMID 37080966, 2023). "Intriguingly, caspase-1 was activated upon infection with wild-type M. ulcerans as well as infection with a plasmid-cured strain, suggesting that capase-1 activation is induced in a mycolactone-independent manner." (PMID 37910490, 2023). "The mutant S. aureus ALC837 infection was unable to induce caspase-1 activation under identical conditions, demonstrating that α toxin is needed for the S. aureus-induced activation of the NLRP3 inflammasome." (PMID 38089811, 2023). "On the other hand, the infection triggered activation of caspase-1 in a mycolactone-independent manner." (PMID 37910490, 2023). "At 15 weeks post infection, we detected increased parasite loads in the ears of Gsdmd–/–, Nlrp3–/–, and Casp1/11–/– as compared to WT mice." (PMID 36828815, 2023). "In infections with Salmonella and Burkholderia species, caspase 1 induced pyroptotic cell death in addition to the clearance of bacteria by reactive oxygen species in neutrophils, and moreover, this occurred without the release of IL-1b and IL-18." (PMID 37998332, 2023). "The expression of caspase 1 and IL-1β was then assessed via immunoblotting or ELISAs in cell extracts or supernatants at 18 and 24 h post-infection (p.i.)." (PMID 37375491, 2023). "ELISA result showed that the IL-1β production was reduced in Caspase-1-/- BMDMs compared with that in WT BMDMs during infection." (PMID 37457695, 2023). "After 6 h of infection, caspase 1 activity was lowered in SC-236 treated cells in both the uroepithelial cells T-24 and 5637." (PMID 37697284, 2023). "Mice deficient in caspase 1 and infected with virulent IOE died from an infection early in comparison to wild-type mice." (PMID 37998332, 2023).
infection (continued). "Consistently, the bacterial burdens were significantly decreased in the WT-mice spleen, liver and cecum after infection compared to Casp1-/—mice, indicating that the activation of Caspase-1-dependent inflammasome was essential for the clearance of SE in mice." (PMID 37155697, 2023). "Further, only Gsdmd–/– BMMs displayed release of cytochrome c from the mitochondria to the cytosol during infection, as expected by faster signaling from caspase-1 to BID." (PMID 38055781, 2023). "To explore the potential effects of direct inflammasome inhibition in vivo, we next evaluated the caspase-1 inhibitor VX-765 administrated as early as day 2 post-infection and for 21 consecutive days." (PMID 36800238, 2023). "The inflammasome–caspase-1–IL-1/IL-18 axis is a relatively newly discovered innate immune pathway that is activated in response to infection and deleterious injury." (PMID 35740095, 2022). "Propionibacterium acnes-mediated stimulation of THP-1 cells had a direct correlation with the expression of active caspase-1 and interleukin (IL)-1β in an infection-dependent manner." (PMID 35871079, 2022). "We have previously determined that PA103 infection of PMVECs elicits activation of the inflammasome-caspase-1 axis." (PMID 35202178, 2022). "Similar to the isogenic PA103 strains, the addition of NAC or Ebselen significantly decreased caspase-1 activation levels during JA817 infection." (PMID 35202178, 2022). "By knocking down AIM2, the authors showed significantly decreased activation of caspase-1 in response to infection with vaccinia virus." (PMID 36298668, 2022). "The NLRP3 inflammasome mediates activation of caspase-1 and secretion of IL-1β in response to infection and cellular damage." (PMID 35720309, 2022). "Infection with Bacillus anthracis also activates multiple cell death effectors, including caspase-1, -8, and -3." (PMID 35563804, 2022). "MERS-CoV infection of HMECs resulted in upregulation of 0.73, 2.7, 2.7, and 4.46% of caspase 1 SGs at 12-, 24-, 36-, and 48-h post-infection, respectively." (PMID 35320939, 2022). "Their discoveries likewise feature the need to return to the job of caspase-1 versus caspase-11 in various mouse infection models, as so far, all investigations have utilized Casp1/11 twofold knockout mice." (PMID 35572571, 2022). "The infection of casp-1−/− and gsdmd−/− cells confirmed that Kp52145-induced cell death was caspase-1 and GSDMD dependent." (PMID 35947948, 2022). "Caspase-1 is also involved in the cytoplasmic recognition of L. pneumophila flagellin by mouse macrophages, thereby limiting their infection." (PMID 36189207, 2022). "Although multiple neutrophil death programs contribute to host defense against infections, neutrophils are thought to be defective in Caspase-1-dependent pyroptosis." (PMID 35849616, 2022). "Our results showed that EV-A71 infection increased the expression of cleaved caspase-1 in supernatants collected from infected THP-1 macrophages." (PMID 36503883, 2022). "We found 26 proteins that were significantly altered by the CFT073 infection in caspase-1, caspase-4 or NLRP3-knockdown cells compared to CFT073 stimulated Cas9 control cells or compared to their own unstimulated controls." (PMID 35132157, 2022). "When we stratified the participants into subgroups, Caspase-1 exhibited comparable expression levels in NAFLD, NASH, and HCV-nMet, while it was significantly more abundant in subjects with HCV-infection associated with the metabolic disorder (HCV-Met)." (PMID 35806450, 2022). "Our previous study has shown that P. multocida activates NLRP3 inflammasome, subsequently induces caspase-1 activation which process pro-IL-1β into biologically active IL-1β, leading to IL-1β secretion and inflammatory response against infection." (PMID 35350616, 2022).